MCL1 (MCL1 apoptosis regulator, BCL2 family member)
Diseases named in the same sentence as MCL1 in open-access papers (continued):
Sharing a sentence is not in itself a finding about the gene and the disease.
glioma (continued). "One publication postulates that the inhibition of Mcl-1, but not the simultaneous inhibition of Bcl-2, Bcl-w, and, Bcl-xL with ABT-737 sensitizes glioma cells to TMZ42." (PMID 36273072, 2022). "Interestingly, cg00300298 methylation was similar across all 3 histone-altered pHGG subtypes, indicating that MCL1 dependency is not a subtype-specific vulnerability, but instead, it is a common phenotype across a spectrum of WHO-defined childhood gliomas." (PMID 39846250, 2025).
pancreatic cancer (79 papers, 2005 to 2025). "causes growth inhibition of pancreatic cancer cells by inducing p21 expression and cell cycle arrest, and down-regulates the expression of Mcl-1." (PMID 27875574, 2016). "In this study, we clarify the mechanism of Mcl-1 degradation, investigate the metabolic role of Mcl-1 and propose one of the underlying molecular mechanisms of chidamide in pancreatic cancer." (PMID 27875574, 2016). "Knockdown of Mcl-1 led to the cell death in a pancreatic cancer cell line, and loss of Mcl-1 sensitized the cancer cells to Gemcitabine." (PMID 26078955, 2015). "This study evaluated the association between GnP’s therapeutic effects and Mcl-1 expression in tissue samples obtained using endoscopic ultrasound-guided fine-needle aspiration (EUS-FNA) for pancreatic tumor or percutaneous ultrasound-guided biopsy for metastatic liver tumor." (PMID 39304727, 2024). "Serine and arginine-rich splicing factor 1 (SRSF1) and heterogeneous nuclear ribonucleoprotein K (hnRNPK) were aberrantly upregulated in pancreatic cancer, leading to the increased expression of anti-apoptotic splice variants of Bcl-x and Mcl-1, significantly affected responses to chemotherapy." (PMID 31552163, 2019). "Thus, MCL1, which is associated with sensitivity to both antitubulin therapy and gemcitabine, is an important protein mediating chemoresistance in pancreatic cancer." (PMID 29348852, 2017). "Triptolide mediated miR-204 increase causes pancreatic cancer cell death via loss of Mcl-1." (PMID 24025188, 2013). "Since Mcl-1 is up-regulated in pancreatic cancer and loss of Mcl-1 leads to cell death, we investigated whether triptolide decreases levels of Mcl-1 in these cells." (PMID 24025188, 2013). "Interestingly, at least one other study has noted that altered regulation of apoptosis-regulating genes including MCL-1 appears to be associated with acquired chemoresistance of pancreatic cancer cells." (PMID 15956974, 2005). "Here, we show that FLIPinB enhances the cell death in pancreatic cancer cells induced by combinatorial treatment with DL, gemcitabine and Mcl-1 inhibitor S63845." (PMID 39753884, 2025). "In pancreatic cancer cells, the protein Mcl‐1, which is a member of the Bcl‐2 family, also has a role in preventing autophagy‐induced cell death." (PMID 38690008, 2024). "Trichostatin A (TSA) and SK-7041 caused G2/M cell cycle arrest by upregulating p21 and downregulating cyclin B1, the anti-apoptotic protein Mcl-1, and Bcl-XL in pancreatic cancer cell lines." (PMID 37628767, 2023). "KL-6 treatment also resulted in the downregulation of Bcl-2 and MCL1, two genes that suppress apoptosis, suggesting that KL-6 triggers apoptosis in pancreatic cancer cells." (PMID 37927794, 2023). "Using a competitive fluorescence polarization assay and computational method, a UK group found that small molecule NSC146771 was a selective Mcl-1 inhibitor in pancreatic cancer cells." (PMID 37481672, 2023). "Another study reported the mechanism by which TW-37 elicits its action using BxPC-3 and Colo-357 pancreatic cancer cells, which had high levels of Bcl-2, Bcl-xL, and Mcl-1." (PMID 36975494, 2023). "Gemcitabine (Gem) is a first-line agent for the treatment of pancreatic cancer but most cancers develop resistance to gemcitabine due to the higher expression of Mcl-1." (PMID 36077660, 2022). "Baicalein encourages apoptosis in pancreatic cancer cells via anti-apoptotic Mcl-1 protein downregulation." (PMID 36432119, 2022). "The overexpression of the myeloid cell leukemia-1 factor (Mcl-1) has emerged as a promising target for pancreatic cancer." (PMID 36077660, 2022). "UMI77 is a selective inhibitor of Mcl-1 that dissociates Mcl-1 from the pro-apoptotic protein Bak and produced significant radiosensitization in pancreas cancers." (PMID 35875060, 2022).
pancreatic cancer (continued). "Other researchers have demonstrated that TSA and valproic acid (VPA) increase the pro-apoptotic Bim level and reduce the anti-apoptotic Mcl-1 level in pancreatic cancer (Panc1 and PaCa44) cells." (PMID 34659660, 2021). "In pancreatic cancers, chidamide augments gemcitabine-induced cell growth arrest and apoptosis by downregulating the antiapoptotic gene MCL-1." (PMID 34194495, 2021). "It was shown that the NOXA/MCL-1 ratio has an important role in glucose limitation-mediated apoptosis and also in the pancreatic cancer cell proliferation." (PMID 33923896, 2021). "UMI-77 was the first designed molecule with selected affinity for Mcl-1, showing in vivo tumor growth inhibition in models of pancreatic cancer." (PMID 32455818, 2020). "Chidamide inhibits mitochondrial respiration of pancreatic cancer cells by promoting Mcl-1 degradation through the ubiquitin-proteasome pathway." (PMID 33192510, 2020). "In another report, the use of gemcitabine (Gem) in combination with Myeloid cell leukemia 1 (MCL1)-targeting siRNA in loaded liposomes was shown to be effective in treating pancreatic cancer." (PMID 32532030, 2020). "Several compounds, notably 18, 20, 21, 23, and 24, displayed activity towards the pancreatic cancer cell lines BxPC‐3, known to overexpress Mcl‐1, and MiaPaCa‐2, which overexpresses both Mcl‐1 and Bcl‐2." (PMID 28670766, 2017). "Metformin in combination with aspirin was found to synergistically induce apoptosis in a mouse model of pancreatic cancer by downregulating Mcl-1, which strengthens the potential therapeutic application of our findings." (PMID 28881582, 2017). "The MCL-1-specific inhibitor UMI-77, which selectively binds to the BH3-binding groove of MCL-1, inhibits cell growth, induces apoptosis in pancreatic cancer cells and effectively inhibits BxPC-3 xenograft tumor growth." (PMID 28659182, 2017). "Baicalein can promote pancreatic cancer cell apoptosis through up-regulating Bax and down-regulating Bcl-2 and Mcl-1, which has been reported by other groups." (PMID 28915595, 2017). "In previous studies, elevated MCL1 levels were found to induce resistance to antitubulin therapies, such as paclitaxel and vincristine, and MCL1 gene silencing induced apoptosis and increased chemosensitivity to gemcitabine in pancreatic cancer." (PMID 29348852, 2017). "Compounds 16–25 were examined to determine if they displayed activity towards pancreatic cancer cells, which are known to overexpress members of the Bcl‐2 family, including Mcl‐1." (PMID 28670766, 2017). "At first, we found chidamide, an HDAC inhibitor, significantly increased acetylated level of Mcl-1 in pancreatic cancer cells." (PMID 27875574, 2016). "Chidamide exerts anti-tumor effects by inducing Mcl-1 degradation via the ubiquitin- proteasome pathway, promoting apoptosis and inhibiting aerobic respiration of pancreatic cancer cells." (PMID 27875574, 2016). "Mcl-1 is highly expressed in pancreatic cancer cells, and its function in mitochondrial aerobic metabolism has been demonstrated." (PMID 27875574, 2016). "Chidamide induces Mcl-1 degradation through the ubiquitin-proteasome pathway, and consequently inhibits the aerobic metabolism and proliferation of pancreatic cancer cells." (PMID 27875574, 2016). "In this study, both RES and TRES inhibited cell viability in a dose- and time-dependent manner, and TRES had comparative effects of RES on inducing apoptosis by the down-regulation of Mcl-1, and the up-regulation of Bim and Puma, in pancreatic cancer cells." (PMID 27539371, 2016). "We measured the ubiquitinated level of Mcl-1 in pancreatic cancer cells treated with 50 μM chidamide for 24 h by immunoprecipitation and Western blot analysis." (PMID 27875574, 2016). "Mcl-1, as an anti-apoptotic member of the Bcl-2 family, is highly expressed in human pancreatic cancer." (PMID 27875574, 2016).
pancreatic cancer (continued). "After treating the BxPC-3 cells for 24 h with Trichostatin A, immunoprecipitation and Western blot results indicated that TSA also promoted Mcl-1 ubiquitination and decreased Mcl-1 protein levels in pancreatic cancer cells." (PMID 27875574, 2016). "TRES, similarly to RES, inhibited the phosphorylation of STAT3 and NFκB, down-regulated Mcl-1, and up-regulated Bim and Puma in pancreatic cancer cells." (PMID 27539371, 2016). "Pancreatic cancer cells were treated with Mcl-1 siRNA or 50 μM chidamide for 24 h, and then the ATP production and O2 consumption were measured." (PMID 27875574, 2016). "Mcl-1 amplification is one of the most common genetic aberrations observed in human cancers, including pancreatic cancer, indicating Mcl-1 plays a key role in pancreatic tumorigenesis." (PMID 26056043, 2015). "Studies also showed that Mcl-1 highly expressed in pancreatic cancer cells which was related to the resistance to chemotherapeutic drugs." (PMID 26056043, 2015). "In our study, AZD8055, an mTOR inhibitor, significantly decreased the phosphorylation of S6K, resulting in repression of the expression of Mcl-1 in the two pancreatic cancer cell lines." (PMID 26056043, 2015). "Overexpression of miR-204, either by a miR-204 mimic or by triptolide treatment, downregulates myeloid cell leukemia-1 (Mcl-1) by directly binding to the Mcl-1 3′ UTR and causes a subsequent decrease in cell viability and pancreatic cancer cell death." (PMID 24899890, 2014). "Our data suggest that over-expression of miR-204 induces down-regulation of Mcl-1 in pancreatic cancer cells." (PMID 24025188, 2013). "Over-expression of miR-204, either by triptolide treatment or a miR-204 mimic transfection results in suppression of Mcl-1 expression and cell death, both in pancreatic cancer cells and human patient xenografts." (PMID 24025188, 2013). "We therefore conclude that siRNA-mediated Mcl-1 knockdown induces pancreatic cancer death through apoptosis in MIA PaCa-2 cells and autophagy in S2-VP10 cells." (PMID 24025188, 2013). "Twenty-eight human pancreatic cancer sections were stained for Mcl-1 and expression was detected in 23 of 28 human pancreatic cancer tissues (82.14%)." (PMID 24025188, 2013). "Our data, taken together, suggests that triptolide induces pancreatic cancer cell death via down-regulation of Mcl-1 and increased expression of miR-204." (PMID 24025188, 2013). "Using pancreatic cancer cell lines, we have shown that miR-204, a putative regulator of Mcl-1, is repressed in cancer cell lines compared to normal cells." (PMID 24025188, 2013). "To evaluate the role of Mcl-1 expression in survival of pancreatic cancer cells, we decreased levels of Mcl-1 using Mcl-1 specific siRNA." (PMID 24025188, 2013). "In the presence of miR-204 mimic, Mcl-1 protein levels decreased, suggesting that miR-204 targets Mcl-1 in pancreatic cancer cells." (PMID 24025188, 2013). "Our data therefore show that Mcl-1 over-expression in pancreatic cancer cells is due to down-regulation of miR-204." (PMID 24025188, 2013). "Down-regulation of Mcl-1 results in pancreatic cancer cell death, either via apoptosis or autophagy." (PMID 24025188, 2013). "In our study, over-expression of miR-204 results in decrease in Mcl-1 expression and subsequent cell death in pancreatic cancer cells." (PMID 24025188, 2013). "We have shown that triptolide up-regulates miR-204 and down-regulates Mcl-1, an anti-apoptotic protein essential for the survival of multiple cell lineages, and among one of the amplified genes in pancreatic cancer cells." (PMID 24025188, 2013). "Once we had established that Mcl-1 is required for pancreatic cancer cell survival, we investigated the mechanism of regulation of Mcl-1." (PMID 24025188, 2013). "We also use LC3 immunofluorescence assay to detect autophagy in S2-VP10 pancreatic cancer cells after Mcl-1 siRNA transfection." (PMID 24025188, 2013).
pancreatic cancer (continued). "Fifth, overexpression studies in pancreatic cancer cells indicated that both caspase-8 (CrmA) and NF-κB-dependent mitochondrial proteins (Bcl-2, and Mcl-1) were involved in the process of TRAIL sensitization." (PMID 22829912, 2012). "Anti-apoptotic Bcl-2 family proteins Mcl-1, Bcl-XL, and Bcl-2 have been reported to be highly expressed in pancreatic cancer cells, and to contribute to apoptosis resistance." (PMID 22829912, 2012). "Another anti-apoptotic Bcl-2 family member that is highly overexpressed in pancreatic cancer cells is Mcl-1." (PMID 24212603, 2010). "Defects in apoptotic pathways and the deregulation of apoptotic proteins, such as Survivin, Bcl-2, Bcl-xL and Mcl-1, play decisive roles in the development of pancreatic cancer." (PMID 24212603, 2010). "In contrast, ABT-737 induces distinct apoptosis of pancreatic cancer cells after the depletion of MCL-1." (PMID 18652674, 2008). "From a therapeutically viewpoint, dependency of survival of pancreatic cancer cells onto MCL-1 has to be kept in mind, when molecular targeted therapies, like ABT-737 treatment, are considered." (PMID 18652674, 2008). "Antiapoptotic protein, including Mcl-1, expression is frequently observed in pancreatic cancer." (PMID 39304727, 2024). "Mcl‐1 protein prevents autophagy‐induced cell death in pancreatic cancer." (PMID 38690008, 2024). "It was proved that the combination of metformin and aspirin significantly inhibited tumor growth and downregulated the protein expression of Mcl-1 and Bcl-2 in tumors in the xenotransplantation mouse model, which has preventive significance for the occurrence of pancreatic cancer." (PMID 36829129, 2023). "Additionally, Amcp, one novel derivative of valepotriate significantly inhibited the PI3K/AKT signaling, suppressing the cell viability and Mcl-1 expression in pancreatic cancer cells." (PMID 34376189, 2021). "Moreover, defects in apoptotic pathways and the deregulation of apoptotic proteins, such as Bcl-2, Bcl-xL and Mcl-1, play decisive roles in the development and therapy resistance of pancreatic cancer." (PMID 31269745, 2019). "Our study demonstrates that after the knockdown of PKCι, the expression of the transcriptional co-activator YAP1 is decreased, which hinders the expression of the downstream target gene Mcl-1, and subsequently sensitizes pancreatic cancer MiaPaCa and PANC-1 cells experssing mu-Kras to apoptosis." (PMID 30214681, 2018). "Also, in pancreatic cancer cells the Noxa/Mcl-1 balance constitutes a (predictive) factor determining BTZ sensitivity." (PMID 29184971, 2018). "The balance of Noxa and Mcl-1 appeared a good indicator for PI-induced apoptosis and could predict the effectivity of PIs in pancreatic cancer cells." (PMID 29184971, 2018). "Gossypol also inhibits Bcl-2 and Mcl-1 gene expression in pancreatic cancer cells." (PMID 29993017, 2018). "Therefore, it is important to investigate the role of FBXW7 expression, which regulates MCL1, in pancreatic cancer." (PMID 29348852, 2017). "Furthermore, we demonstrated MCL1 is a key substrate of FBXW7 involved in chemotherapeutic resistance in pancreatic cancer." (PMID 29348852, 2017). "In conclusion, our results suggest that chidamide promotes Mcl-1 degradation through the ubiquitin-proteasome pathway, suppressing the maintenance of mitochondrial aerobic respiration by Mcl-1, and resulting in inhibition of pancreatic cancer cell proliferation." (PMID 27875574, 2016). "In fact, Takahashi and co‐workers have recently reported that Bcl‐xL and Mcl‐1 might co‐operatively play a role in the apoptotic cell death of pancreatic cancer and that targeting both proteins may be a viable therapeutic strategy." (PMID 26616140, 2016). "Next we investigated the function of Mcl-1 downregulation by chidamide in pancreatic cancer cells." (PMID 27875574, 2016). "Additionally, a report has suggested that knockdown of Bcl-xL or Mcl-1 can induce apoptosis in pancreatic cancer cells." (PMID 26506422, 2015).